RLIM (ring finger protein, LIM domain interacting)
Description:
E3 ubiquitin-protein ligase that acts as a negative coregulator for LIM homeodomain transcription factors by mediating the ubiquitination and subsequent degradation of LIM cofactors LDB1 and LDB2 and by mediating the recruitment the SIN3a/histone deacetylase corepressor complex. Ubiquitination and degradation of LIM cofactors LDB1 and LDB2 allows DNA-bound LIM homeodomain transcription factors to interact with other protein partners such as RLIM. Plays a role in telomere length-mediated growth suppression by mediating the ubiquitination and degradation of TERF1. By targeting ZFP42/REX1 for degradation, acts as an activator of random inactivation of X chromosome in the embryo, a stochastic process in which one X chromosome is inactivated to minimize sex-related dosage differences of X-encoded genes in somatic cells of female placental mammals. E3 ubiquitin-protein ligase is required for proper regulation of neural cell differentiation from embryonic stem cells (By similarity).
Synonyms: RNF12; NY-REN-43; MGC15161; MRX61; TOKAS
Tractability: PROTAC: ubiquitination databases record sites on it.
Gene: Protein-coding gene on chromosome X (74,582,976 to 74,614,627, reverse strand). Ensembl gene ENSG00000131263.
Subcellular location: Nucleus
Subcellular location (Human Protein Atlas): Nucleoplasm; Cytosol
Pathways (Reactome):
Immune System: Antigen processing: Ubiquitination & Proteasome degradation
Gene Ontology:
Molecular function: ubiquitin protein ligase activity; ubiquitin-protein transferase activity; transcription corepressor activity
Biological process: protein ubiquitination; random inactivation of X chromosome; negative regulation of DNA-templated transcription; ubiquitin-dependent protein catabolic process; regulation of neurogenesis
Cellular component: nucleoplasm; nucleus; cytosol; transcription repressor complex
Homologues: Orthologues: macaque RLIM (99% identical), chimpanzee RLIM (99% identical), dog RLIM (97% identical), pig RLIM (96% identical), rabbit RLIM (94% identical), rat Rlim (87% identical), mouse Rlim (86% identical), tropical clawed frog rlim (66% identical), guinea pig RLIM (60% identical), zebrafish rlim (55% identical). Paralogues in human: RNF6 (42% identical), RNF38 (16% identical), RNF44 (12% identical).
Diseases named in the same sentence as RLIM in open-access papers:
RLIM is named in the same sentence as 23 diseases in open-access papers, as found by Europe PMC text mining. Sharing a sentence is not in itself a finding about the gene and the disease. The quoted sentences say what the papers report.
Intellectual disability (8 papers, 2017 to 2024). "The E3 ubiquitin ligase RNF12/RLIM is mutated in intellectual disability and controls developmental gene expression." (PMID 38199845, 2024). "In support of this notion, RNF12/RLIM amplifications, in addition to deleterious variants, have been associated with neurological phenotypes and facial features characteristic of impaired developmental and intellectual disability." (PMID 37607329, 2023). "Variants in RLIM that disrupt RNF12 E3 ubiquitin ligase activity cause TOKAS, a developmental disorder characterized by intellectual disability and syndromic anomalies including urogenital defects with hypogenitalism in affected males and fertility defects in heterozygous carrier females." (PMID 35857630, 2022). "Mutations of both RLIM and ZC4H2 were reported to be associated with human intellectual disability." (PMID 35040952, 2022).
breast carcinoma (6 papers, 2021 to 2025). "RLIM appears to be a regulator of estrogen-dependent transcription, an important pathway in breast cancer, and has been recently described as a potential tumor suppressor." (PMID 39132489, 2024).
osteosarcoma (2 papers, 2022 to 2024). A usually aggressive malignant bone-forming mesenchymal neoplasm, predominantly affecting adolescents and young adults. "It was also reported that RLIM promotes cell migration in osteosarcoma cells by regulating TGF-β signaling." (PMID 35040952, 2022). "Additionally, the direct binding of E3 ligases Smad ubiquitination-related factor 1 (Smurf2) with E3 ubiquitin ligase RLIM (RING finger LIM domain-binding protein) markedly enhances the response of osteosarcoma U2OS cells to TGF-β (transforming growth factor-β)." (PMID 39062505, 2024).
Azoospermia (1 paper, 2022). Absence of any measurable level of sperm,whereby spermatozoa cannot be observed even after centrifugation of the semen pellet. "Finally, we showed that the RNF12-USP26 axis was disrupted by RLIM variants from TOKAS patients, whereas RNF12 stabilization and downstream transcriptional regulation was disrupted by USP26 gene variants identified from azoospermia patients." (PMID 35857630, 2022).
hepatocellular carcinoma (1 paper, 2017). A malignant tumor that arises from hepatocytes. "In addition, we showed that RLIM overexpression suppresses the cell growth and arrests cell cycle progression of hepatocellular carcinoma." (PMID 29137325, 2017).
intellectual disability syndrome (1 paper, 2020). "In mammalian embryonic stem cells and cultured neurons, SRPK phosphorylates Ser-Arg motifs in RNF12/RLIM, a key developmental E3 ubiquitin ligase that is mutated in an intellectual disability syndrome." (PMID 33080171, 2020).
tumor (8 papers, 2017 to 2025). "To test the role of RLIM in MB progression, we injected Daoy cells stably transfected with RLIM shRNA into mice and found that RLIM knockdown led to reduced tumor size in vivo." (PMID 35040952, 2022).
cancer (6 papers, 2016 to 2025). A tumor composed of atypical neoplastic, often pleomorphic cells that invade other tissues. "Here, we identified RLIM as a novel E3 ubiquitin ligase for c-Myc, one of the most frequently deregulated oncoproteins in human cancers." (PMID 27684546, 2016). "Our findings reveal a tumor suppressor role for RLIM which could potentially be exploited for cancer treatment." (PMID 27684546, 2016). "Genes such as RLIM, FBL17, FGF7, DDX5, NAV3, and NFASC were found at the intersection of multiple pathways, suggesting they may function as critical effectors of miR-155 and miR-3173 activity in cancer." (PMID 40722677, 2025).
infection (1 paper, 2023). The state of being infected such as from the introduction of a foreign agent such as serum, vaccine, antigenic substance or organism. "For example, LANA can disrupt host transcriptional activities early after infection by directly interacting with RLIM, a RING domain containing E3 ubiquitin ligase also known as RNF12, thereby enhancing its autoubiquitination and degradation." (PMID 37766341, 2023).
RLIM also shares sentences with these, for which no sentence is quoted: neurodevelopmental disorder (3 papers); glioblastoma (2); X-linked intellectual disability (2); breast tumor (1); Cerebellar atrophy (1); colon cancer (1); diaphragmatic hernia (1); Fryns syndrome (1); Gordon Holmes syndrome (1); invasive breast carcinoma (1); liver cancer (1); stomach cancer (1); thyroid cancer (1); triple-negative breast carcinoma (1).